INSR (insulin receptor)
Diseases named in the same sentence as INSR in open-access papers (continued):
Sharing a sentence is not in itself a finding about the gene and the disease.
Obesity (continued). "Insulin activated the insulin receptor, as indicated by increased insulin receptor Tyr1162 phosphorylation in all cell lines regardless of their correlation, or lack thereof, with obesity." (PMID 31188872, 2019). "Similar to tissue fat content, exercise did not ameliorate the obesity‐induced decrease in the InsR and accentuated the obesity‐induced upregulation of AKT activation (pAKT T308) in the maternal liver, compared to lean controls." (PMID 31466137, 2019). "Patients with IR due to monogenic lipodystrophy or insulin receptor (INSR) mutations present with AE, ovulatory dysfunction, PCO and acanthosis nigricans, usually in the absence of obesity." (PMID 28566439, 2017). "Type 2 diabetes and obesity have characteristics of inflammatory conditions with increased blood levels of pro-inflammatory cytokines, such as interleukin (IL)-6, IL-1 and TNF-α, which attenuate insulin receptor signaling." (PMID 19114996, 2008). "Indeed, obesity induces increased expression of TNF-α and NFκB, leading to down-regulation of insulin receptor and decreasing expression of GLUT4." (PMID 17107852, 2006). "Indeed while knockout of the insulin receptor in SF-1 neurones induces resistance to high fat diet-induced obesity, knockout of the main metabolic PI3K catalytic subunit, p110α, also in SF-1 neurones, reduced energy expenditure and promotes obesity." (PMID 40152560, 2025). "Working with a rodent model that mimics metabolic syndrome via hypothalamic insulin receptor downregulation (hypo‐IRAS rats), they found that obesity‐induced anhedonia—operationalized via reduced sucrose preference—could be both prevented and reversed by implementing dietary restriction." (PMID 40129874, 2025). "Therefore, coupled with the finding that obesity does not increase InsR expression in the ArcN, the markedly amplified increases in SNA evoked by insulin must be secondary to increases in insulin-induced cellular signaling in the ArcN." (PMID 32160920, 2020). "Interestingly, mice with an adipose tissue specific insulin receptor knockout (FIRKO mice) show a normal glucose tolerance and insulin sensitivity and are protected against obesity-related glucose intolerance, which resemble the Nscl-2 phenotype to certain degree." (PMID 19436734, 2009). "Maternal overweight/obesity did not increase the risk of CSFK in these children, possibly because the increased maternal glucose levels do not result in increased cellular uptake of glucose in children with the SNV because of their lower insulin receptor activity." (PMID 37738450, 2024). "The effect of T2D on insulin receptor expression in liver and skeletal muscles has not been extensively studied but the available evidence suggests that there is no cell surface receptor deficit in people with obesity and T2D compared with obese control participants." (PMID 35054781, 2022). "Type A insulin resistance (IR) syndrome is a very uncommon genetic disorder affecting the insulin receptor (INSR) gene, characterized by severe IR without the presence of obesity." (PMID 35498407, 2022). "This does not appear to be due to a decrease in the expression of InsR in NPY neurons; therefore, obesity in females somehow attenuates insulin signaling specifically in presympathetic ArcN neurons." (PMID 32160920, 2020).
type 2 diabetes (244 papers, 2004 to 2026). "Zn also enhances insulin receptor signaling, improving glucose uptake and reducing the risk of type 2 diabetes." (PMID 41459237, 2025). "Its inhibition disrupts insulin receptor signaling, leading to impaired glucose uptake and hyperglycemia, particularly in individuals predisposed to Type 2 diabetes or metabolic disorders." (PMID 39861189, 2025). "Type 2 diabetes begins with a gradual decline in insulin effectiveness, causing the body to struggle with glucose transport into tissues and leading to insulin receptor desensitization." (PMID 39588429, 2024). "While in type 1 diabetes the major problem causing physiological and cognitive deficits is insulin deficiency, in type 2 diabetes it is the malfunctioning of insulin receptor activity that has enormous consequences on the brain." (PMID 36232867, 2022). "Type 2 diabetes-like conditions and loss of insulin receptor function in multidendritic sensory neurons lead to mechanical nociceptive hypersensitivity." (PMID 34549177, 2021). "Further, there were also records associated with glucose metabolism (type 2 diabetes, positive regulation of glucose metabolic process, signaling of insulin via INSR, IGF1R, PKB, Pi3K, and MAPK)." (PMID 33445738, 2021). "This study assesses glucose, total InsulinT, Insulin2 and insulin receptor subunits α and β in testis during mouse development then, in the spontaneously type 2 diabetes models associated with infertility db/db and ob/ob mice." (PMID 32183843, 2020). "On the other hand, TIMP3 deficiency in insulin receptor-haploinsufficient mice promotes type 2 diabetes and vascular inflammation." (PMID 27126782, 2016). "Protein tyrosine phosphatase 1B (PTP1B) is implicated as a negative regulator of insulin receptor (IR) signaling and a potential drug target for the treatment of type II diabetes and other associated metabolic syndromes." (PMID 24481115, 2014). "This disruption in insulin receptor activation can have significant metabolic consequences, particularly for individuals at risk of or already suffering from metabolic disorders such as Type 2 diabetes." (PMID 39861189, 2025). "Additionally, upregulated CELF1 contributes to the mis-splicing of several genes, including those encoding chloride channels, sodium channels, and the insulin receptor, which are linked to key clinical symptoms of myotonia and type 2 diabetes mellitus (T2DM)." (PMID 41303475, 2025). "It was previously reported that TNF-α interferes with the insulin receptor signaling pathway and with metabolism of glucose transporters, and in consequence may be linked to the etiology of type-2 diabetes." (PMID 37514235, 2023). "Diabetes type 2 may be associated with INSR, which involved in adipogenesis and beta-cell insulin secretion." (PMID 37063851, 2023). "Estrogen is known to regulate insulin receptor expression on peripheral tissues, especially on adipocytes, and is also involved in pathways associated with other cardio‐metabolic dysfunction such as dyslipidaemia, hypertension and type 2 diabetes." (PMID 35596933, 2022). "Finally, PIP4K a key enzyme in the regulation of PI5P levels has been recently implicated in the control of insulin receptor signalling and Type II diabetes." (PMID 31652444, 2019). "Type I diabetes mellitus is associated with pancreatic β cell dysfunction resulting in the loss of insulin production, whereas type II diabetes mellitus is caused by insulin receptor dysfunction in which insulin receptor signaling is uncoupled from glucose uptake." (PMID 27547766, 2016). "The fact that hyperinsulinemia is a pathological hallmark of type 2 diabetes, along with the structural and functional homology between INSR and IGF1R, prompted us to further investigate the potential roles of insulin and INSR in PCa development and progression." (PMID 24434591, 2014).
type 2 diabetes (continued). "Correct intracellular trafficking of the InsR is critical for insulin sensitivity and it has been shown that mutations in the InsR gene that impair the transport of the receptor to the plasma membrane lead to type 2 diabetes in humans." (PMID 17987120, 2007). "The personal fat threshold hypothesis proposes that in susceptible individuals, excessive ectopic fat accumulation may eventually lead to hepatic insulin receptor resistance, the loss of pancreatic insulin secretion, hyperglycemia and the development of frank type 2 diabetes." (PMID 38791525, 2024). "Thus, it is possible that renal deficiencies in InsR signaling may be expected to be a greater driver of progression to type 2 diabetes in males when compared to females, while females may present earlier with electrolyte/blood chemistry disorders." (PMID 37175762, 2023). "The pathogenesis of type 2 diabetes involves two primary metabolic defects: impaired insulin secretion and insulin resistance, defined as a reduction of tissue insulin sensitivity caused by a loss/downregulation of the insulin receptors (IR) or insulin receptor substrates (IRS-1 and IRS-2)." (PMID 35391928, 2022). "Therefore, the array of mRNA ligands potentially recognized by IMP2, such as the insulin receptor, may inform the mechanism of its association with type II diabetes in humans." (PMID 31570709, 2019). "Insulin signaling plays an important role in the development of type 2 diabetes, and the insulin receptor has been indicated as a substrate of BACE1." (PMID 40507910, 2025). "Its role in insulin signaling pathways is particularly important in the development of type 2 diabetes, as it impacts the efficiency of insulin receptor signaling and glucose uptake, thereby modulating the body’s insulin sensitivity." (PMID 38610028, 2024). "In obese conditions, INSR expression in WAT is decreased, which is linked to the pathogenesis of type 2 diabetes." (PMID 38255206, 2024). "Gene ontology (GO) enrichment analysis showed that the MCODE1 network components were significantly enriched in the insulin receptor signaling pathway and type II diabetes mellitus." (PMID 39348384, 2024). "The study used a rat model where maternal type 2 diabetes was induced by insulin receptor inhibition, and this condition was maintained during pregnancy." (PMID 39759101, 2024). "Mice lacking the INSR gene have hyperglycemia and hyperinsulinemia, and a large number of studies have shown decreased INSR in patients with type 2 diabetes." (PMID 37786444, 2023). "In type II diabetes, insulin binds to the insulin receptor, but there is a failure to activate the insulin signalling cascade, resulting in a loss of glucose transport into cells and ultimately high blood glucose levels." (PMID 37621079, 2023). "We also discuss mechanistic links between altered InsR signaling and immune dysfunction in various disease settings and conditions, with a focus on age related conditions, such as type 2 diabetes, cancer and infection vulnerability." (PMID 36992811, 2023). "The insulin receptor mRNA of the pineal gland was found to be reduced in type 2 diabetic rats, suggesting a functional relationship between melatonin and insulin." (PMID 36768693, 2023). "Insulin–insulin receptor interaction clearly represents the tip of the iceberg in type II diabetes to regulate glucose levels." (PMID 36499769, 2022). "Insulin receptor (IR) signaling is central to normal metabolic control and is dysregulated in metabolic diseases such as type 2 diabetes." (PMID 36473871, 2022). "Alterations in insulin receptor signaling in type 2 diabetes and AD develop due to changes in both major signaling pathways." (PMID 36232867, 2022). "As a result, InsR is regarded as a potential therapeutic target in the treatment of type 2 diabetes and insulin resistance." (PMID 34899318, 2021). "Polymorphisms in the INSR and IRS-1 genes associate with type 2 diabetes mellitus (T2DM) and insulin resistance." (PMID 34408667, 2021).
type 2 diabetes (continued). "Phosphorylated FetA was reported to play a part in insulin resistance in type 2 diabetes mellitus (T2DM) through binding the β-subunit of the insulin receptor and hindering insulin signaling." (PMID 34988120, 2021). "Magnesium supplementation has a positive effect on insulin receptor activity and insulin sensitivity in type 2 diabetes." (PMID 32952944, 2020). "Overall, our study suggests that magnesium supplementation has a positive effect on insulin receptor activity and insulin sensitivity in type 2 diabetes by inhibiting lipid peroxidation and up-regulating β-Arrestin-2 gene expression." (PMID 32952944, 2020). "After high dose magnesium supplementation, the diabetic group showed significantly increased R values, which indicates that magnesium can promote the recovery of insulin receptor capacity in type 2 diabetic rats." (PMID 32952944, 2020). "Our analyses also showed that upon immunization, the type 1 diabetes (T1D), type 2 diabetes (T2D) and insulin receptor signalling (q < 0.05) pathways were predicted to be downregulated." (PMID 31142858, 2019). "Insulin therapy is often needed to overcome insulin receptor resistance in type 2 diabetes; however, the impact of providing additional insulin to already hyperinsulinemic subjects is not clear." (PMID 30249002, 2018). "Insulin receptor (INSR) dysregulation is a well-established defect in type II diabetes mellitus (ko04930)." (PMID 29112983, 2017). "It has been demonstrated that an oral aminoacids mixture significantly improves insulin sensitivity in elderly subjects with sarcopenia or type 2 diabetes, probably by an up-regulation of the insulin-receptor synthesis and its autophosphorylation." (PMID 28532453, 2017). "First, we provide a rare description of insulin allergy associated with hypereosinophilia, anti-insulin IgG antibodies, and anti-insulin receptor antibodies in a patient with type 2 diabetes." (PMID 27456688, 2016). "Previously, we reported inducible insulin receptor knock-down rats which developed type II diabetes within a few days after Dox administration." (PMID 26605921, 2015). "The mouse irs2 has been shown to modulate cell growth and metabolism downstream of insulin receptor signaling, and irs2−/− knockout mice develop type 2 diabetes." (PMID 25840431, 2015). "Type 2 diabetes decreases insulin sensitivity in the brain, insulin transport through the blood–brain barrier, and insulin receptor’s sensitivity, and it alters glucose metabolism and energy utilization." (PMID 25018729, 2014). "Previous research has shown that whether aerobic exercise precedes resistance or vice versa, both sequences improve insulin sensitivity through enhanced glucose absorption and increased insulin receptor activity in patients with type 2 diabetes." (PMID 41499584, 2026). "Bariatric surgery or a very low-calorie diet (VLCD) can quickly reduce ectopic fat from liver and pancreas and decrease intracellular DAG content: this restores hepatic insulin receptor sensitivity, normalizes metabolism, and put type 2 diabetes in many cases in remission." (PMID 41009753, 2025). "Moreover, network pharmacology study involve common targets of bergaptol and type 2 diabetes, which was further applied for gene ontology suggested INSR, NF-κB, Akt and GSK-3β targets for the insulin signalling and resistance both." (PMID 40126146, 2025). "This could be due to a genetic abnormality in the functioning of β cells in the pancreas that produce insulin, known as Type 1 Diabetes, or the denaturation of the insulin receptor, known as Type 2 Diabetes (T2D)." (PMID 39833933, 2025). "Moreover, overexpression of Cav-3 in liver improves insulin sensitivity, insulin receptor signaling and glucose metabolism with increased glycogen synthesis in KKAy mice with type 2 diabetes." (PMID 40012041, 2025).
type 2 diabetes (continued). "Additionally, 4 genes (APOB, INSR, PPARG, APOC3) had prior genetic associations with MASLD while another 12 genes had associations with a MASLD-related phenotype (type 2 diabetes, BMI-adjusted waist-to-hip ratio (WHRadjBMI), metabolic syndrome)." (PMID 40065360, 2025). "The Drosophila pseudokinase Tribbles (Trbl) shares conserved functions with human TRIB3 to bind and inhibit Akt phosphorylation-activation by the Insulin Receptor (InR) to reduce insulin responses; consistent with this, increased levels of human TRIB3 are linked to type 2 diabetes." (PMID 40292740, 2025). "Gene association studies have so far identified 16 candidate loci involved in PCOS, including genes involved in gonadotropin action (LHCGR and FSHR), metabolism and sexual development (ESR1), insulin signaling and type 2 diabetes (INSR, THADA, HMGA2) or cell proliferation (YAP1 and SUMO1P1)." (PMID 40551954, 2025). "In both children and adults, hyper-BCAAemia has been linked to obesity and type 2 diabetes mellitus (T2DM), possibly via chronic overactivation of the mTORC1 pathway, which may impair insulin receptor signaling and exacerbate metabolic inflexibility." (PMID 40725241, 2025). "It has been shown that mice with genetic ablation of Cav-3 exhibit impaired insulin signaling, abnormal glucose and lipid metabolism, adiposity, and insulin resistance with ligand-induced insulin receptor instability in skeletal muscle, which has similar features to type 2 diabetes." (PMID 40012041, 2025). "Metformin and rosiglitazone are first‐line insulin receptor sensitizers in type 2 diabetes." (PMID 38059818, 2024). "Within the context of type 2 diabetes mellitus (T2DM), a pivotal hallmark is the emergence of insulin resistance (IR), wherein aberrations in the signaling pathways downstream of the insulin receptor stand as prime contributors to this pathophysiological state." (PMID 37772084, 2023). "Girls are more likely to develop type 2 diabetes than boys, which may be due to overstimulation of the insulin receptor in pancreatic beta cells by endogenous estrogen." (PMID 36589801, 2022). "The insulin receptor can be affected by palmitic acid, which significantly stimulates insulin secretion and produces hyperinsulinemia, leading to the promotion of the occurrence of type 2 diabetes." (PMID 35465261, 2022). "InsR in muscle also is regulated by Berberine, but mostly, hepatocytes have been studied because hepatic insulin resistance is an important driving force in hyperglycemia and type 2 diabetes." (PMID 34094026, 2021). "The existence of such a minor, albeit metabolically more active pool of fetuin could be important in the pathology of type 2 diabetes which relates to acquired or inherited defects in the insulin receptor signaling cascade." (PMID 31097672, 2019). "The CD47 gene that is a negative modulator of insulin receptor activation and associated with type II diabetes mellitus development, was identified as a direct target of miR‐708." (PMID 31273952, 2019). "Pro-inflammatory molecules (e.g., TNF, IL-6, IL-1β) are increased in type II diabetes and AD, which may compromise the hippocampal insulin receptor expression and/or signaling." (PMID 31291963, 2019). "Interestingly, insulin receptor signaling, type II diabetes, and glucose metabolism were identified in both db/db mouse liver and HepG2 cells treated with ESB." (PMID 28139721, 2017). "Despite the fact that few common genes were identified, we found that many common biological functions such as insulin receptor signaling, type II diabetes, lipid metabolism, and glucose metabolism were enriched in modules from db/db mouse liver and HepG2 cells treated with ESB." (PMID 28139721, 2017). "Similarly, protein tyrosine phosphatase 1B, a type II diabetes target which dephosphorylates insulin receptor, is allosterically inhibited by Benzbromarone and its derivatives." (PMID 28542603, 2017).